CCR3 (C-C motif chemokine receptor 3)
Diseases named in the same sentence as CCR3 in open-access papers (continued):
Sharing a sentence is not in itself a finding about the gene and the disease.
breast cancer (continued). "In summary, we immunolocalized CCL5 and CCR1, 3 and 5 in breast carcinoma tissues and demonstrated that the expression of CCL5 in stromal cells was significantly correlated with tumor progression in a paracrine manner via CCR3 expressed in breast carcinoma cells." (PMID 33671956, 2021). "From these findings, we speculated that CCL5 might promote breast cancer progression via CCR3 but not CCR1 or CCR5." (PMID 33671956, 2021). "In addition, in the previous study, CCR3 was correlated with an improved relapse-free survival in only the luminal type, but not in other types, of breast cancer." (PMID 33671956, 2021). "Taken together with these previous studies and our findings, CCL5 secreted by stromal cells may contribute to tumor progression by activating CCR3 expressed in carcinoma cells and regulating downstream pathways such as ERK signaling in breast carcinoma tissues." (PMID 33671956, 2021). "Actually, the risk of recurrence was significantly higher in patients with breast carcinomas positive for CCL5 and CCR3 but negative for CCR1 and CCR5." (PMID 33671956, 2021). "CCL5 and CCR5 (but not CCR1 and CCR3) are overexpressed in the basal and HER-2+ breast cancer subtypes." (PMID 29216863, 2017). "Notably, four hub genes (SAA1, CCR3, CCR5 and CXCL11) were unique among the breast cancer LM2 cell line; they were not identified among DEGs from the metastatic BrM2 cell line." (PMID 35045088, 2022). "Furthermore, the risk of recurrence was significantly higher in the patients with breast carcinomas positive for CCL5 and CCR3 but negative for CCR1 and CCR5, as compared with other patients." (PMID 33671956, 2021).
Obesity (16 papers, 2012 to 2025). Accumulation of substantial excess body fat. "In our study, the observed increase in migration associated with obesity and ageing is totally abrogated when CCR3 is inhibited." (PMID 33671469, 2021). "The observed increase in migration associated with obesity is totally abrogated when the CCR3/CCL7 axis is inhibited." (PMID 26756352, 2016). "The observed increase in migration associated with obesity is totally abrogated when the CCR3/CCL7 axis is inhibited, highlighting its key role in this altered condition." (PMID 26756352, 2016). "Notably, CCL7 and its respective receptor CCR3, are upregulated in AT in human obesity and are associated with increased inflammation." (PMID 35406450, 2022). "For example, obesity strongly promotes the process by which PPAT-secreting chemokine CCL7 stimulates the migration of CCR3-expressing tumor cells." (PMID 38164282, 2024). "RT-PCR analysis of mRNA obtained from circulating EOS corroborated flow cytometry data, revealing significantly higher levels of expression of CCR3 mRNA in lean patients compared with people with obesity (P = 0.001)." (PMID 38206766, 2024). "The reduction of all eotaxin and CCR3 mRNA in AT from our cohort with obesity provides evidence that an EOS migratory pathway is inhibited during obesity." (PMID 38206766, 2024). "We believe this to be the first report of a reduction of expression of CCR3 in circulating EOS isolated from patients with obesity versus matched lean controls." (PMID 38206766, 2024). "Inhibition of CCR3 completely abrogated the increase of cell migration observed in obesity and during ageing in both PC3 and C4-2B cell lines." (PMID 33671469, 2021). "We have previously demonstrated that adipocytes from PPAT favor the initial step of PPAT infiltration by secreting the CCL7/MCP3 chemokine that attracts CCR3-expressing cancer cells, and this process is amplified in obesity." (PMID 33671469, 2021). "Taken together, our results show that obesity and ageing increased the directed migration of PCa cells by modulating the secretory pattern of adipocytes, this effect being dependent on the CCR3/CCL7 axis." (PMID 33671469, 2021). "In prostate cancer, CCL7, which is secreted by adipocytes, stimulates migration of CCR3-positive tumor cells and acts as a driving force for cancer progression in obesity." (PMID 31963450, 2020). "A previous report showed that obesity-induced periprostatic adipocytes facilitated the extraprostatic extension of PCa cells by enhanced CCR3/CCL7 signaling." (PMID 29340091, 2017). "For whole adipose tissue, the use of pharmacological inhibitors and CCR3/CCL7 blocking m/pAbs completely abrogated the increase of tumour cell migration observed in obesity." (PMID 26756352, 2016). "The upregulation of CCL7 secretion in obesity facilitates extraprostatic extension and increases local dissemination, this effect being totally abrogated when the CCR3/CCL7 axis is inhibited." (PMID 26756352, 2016). "These compelling results show for the first time that CCR3 is expressed in prostate cancer and that its expression, amplified in obesity, is correlated both with the occurrence of aggressive prostate cancer, BCR and surgical treatment failure." (PMID 26756352, 2016). "To determine whether the eotaxin receptor, in addition to the eotaxins, was affected by obesity, we explored whether the expression of CCR3 mRNA and protein was altered in circulating EOS of individuals with differing BMI." (PMID 38206766, 2024). "Notably, depletion of tumor CCR3 completely abolished the ability of obesity to promote tumor metastasis." (PMID 31500625, 2019). "Notably, increased adipose tissue levels of multiple β-chemokines (CCL2, CCL3, CCL5, CCL7, CCL8, CCL11) and chemokine receptors (CCR1, CCR2, CCR3, CCR5) have been linked with obesity and associated metabolic inflammation." (PMID 28396851, 2017).
Obesity (continued). "In conclusion, in mouse models, our compelling results show that CCR3 is therefore a major determinant of prostate cancer progression by influencing tumour size and adipose tissue remodelling and that its effect is substantially influenced by obesity." (PMID 26756352, 2016). "Thus, obesity increases the directed migration of prostate cancer cells by modulating the secretory pattern of mature adipocytes, this effect being mainly dependent on the CCR3/CCL7 axis." (PMID 26756352, 2016). "Upon inhibiting the CCR3/CCL7 axis, the observed obesity-potentiated tumor cell migration and invasion are nullified." (PMID 35406450, 2022). "Another study examined the CCL7/CCR3 axis in a mouse model of PCa and obesity, specifically in the periprostatic adipose tissue surrounding the tumor, finding that this tissue secretes CCL7, which in turn stimulates the migration of CCR3-expressing tumor cells." (PMID 31500625, 2019). "Moreover, depletion of the CCL7/CCR3 axis completely abolishes the ability of obesity to promote tumor metastasis, which reflects the importance of the CCL7/CCR3 axis in prostate cancer in the context of obesity." (PMID 29915688, 2018). "However, the expression of Ccr3 significantly increased in the perigonadal WAT on a HFD, as well as the frequency and number of eosinophils, implying the preferential infiltration of eosinophils into adipose tissue with obesity." (PMID 29967467, 2018). "In addition, it has been previously shown that obesity triggers a modest change in the expression of CCR3 and no change in that of CCR1." (PMID 24895488, 2014).
allergic asthma (13 papers, 2017 to 2025). A asthma with a basis in a pathological type I hypersensitivity reaction. "It has been reported that CCR3 and its ligands can cause airway hyperresponsiveness in a murine allergic asthma model, contributing to ocular allergies." (PMID 36546900, 2022). "CCR3 and its ligands are involved in airway hyperresponsiveness in allergic asthma, ocular allergies, and cancers." (PMID 36546900, 2022). "Allergic asthma is a chronic and heterogeneous pulmonary disease in which platelets can be activated in an IgE-mediated pathway and migrate to the airways via CCR3-dependent mechanism." (PMID 34440807, 2021). "Eotaxin, by acting on CCR3, selectively recruit eosinophils from the airway microvessels into the lung tissue, which plays a central role in the onset of allergic asthma." (PMID 28614408, 2017). "Moreover, the C19 peptide inhibits CCR3-mediated chemotaxis and has excellent therapeutic potential in managing allergic asthma." (PMID 36865551, 2023). "The downregulation of Ccr3 may be developed as a promising approach for the treatment of allergic asthma." (PMID 35409371, 2022). "While anti-IL-5 treatment has been widely approved for treating eosinophilic asthma, attenuation of broad-range inflammatory and physiological changes after allergen challenge suggests that blocking CCR3, IL-3, and GM-CSF are also important targets for the management of allergic asthma." (PMID 33917396, 2021). "C19 peptide inhibited Th2 cell responses, eosinophilia, and AHR in a mouse allergic asthma model by acting on CCR4 and CCR3." (PMID 36865551, 2023).
allergic rhinitis (13 papers, 2006 to 2025). Inflammation of the nasal mucous membranes caused by an IgE-mediated response to external allergens. "In conclusion, decreased eosinophil infiltration by IL-17A deficiency in allergic rhinitis is attributed at least in part to a decreased chemotactic response of eosinophils via the CCL7/CCR3 pathway." (PMID 28046055, 2017). "Based on these data, it was initially discovered that CCR3 mAb can control the clinical symptoms of allergic rhinitis and can affect the pathogenesis of AR by inhibiting inflammatory factors." (PMID 38212473, 2024). "This study aimed to investigate the therapeutic effects of CCR3 monoclonal antibodies on allergic rhinitis in mice." (PMID 38212473, 2024). "Based on the theory of "one airway, one disease", using CCR3 monoclonal antibodies for allergic rhinitis should also have similar effects." (PMID 38212473, 2024). "The CCR3 gene plays a critical role in allergic airway inflammation, such as allergic rhinitis (AR), and there is an inflammatory signal link between the nasal cavity and the CCR3 gene in bone marrow." (PMID 35354939, 2022). "In this study, we assessed the contribution of IL-17A to eosinophil-related inflammation via the CCL7/CCR3 pathway in experimental allergic rhinitis." (PMID 28046055, 2017). "In the present study, CCL7 and CCR3 mRNA levels were significantly increased in the nasal mucosa in an allergic rhinitis." (PMID 28046055, 2017). "This is consistent with previous reports of greater than 90% upregulation of CCL7 and CCR3 gene expression in the nasal mucosa of patients with allergic rhinitis." (PMID 28046055, 2017). "The observation is in keeping with previous findings on such effects by CCR3 antagonism in experimental models, and extends them to include allergic rhinitis." (PMID 20144207, 2010). "AZD3778 exerts anti-eosinophil and symptom-reducing effects in allergic rhinitis and part of this effect can likely be attributed to CCR3-antagonism." (PMID 20144207, 2010). "Therefore, this experiment used CCR3 antibodies to inhibit the actions of CCR3 and treat allergic rhinitis in mice." (PMID 38212473, 2024). "The role and mechanism of CCR3 mAb in allergic rhinitis need further in-depth research." (PMID 38212473, 2024). "In this study, CCR3 mAb was used to treat allergic rhinitis." (PMID 38212473, 2024). "Additionally, studies in allergic rhinitis and pulmonary inflammation demonstrate a critical role of CCR3 expression in the inflammatory pathway and recruitment of eosinophils." (PMID 36733370, 2022). "The suppression of nasal inflammation due of IL-17A deficiency in allergic rhinitis is partly responsible for the regulation of CCL7 secretion and eosinophil infiltration, which may be regulated via the CCL7/CCR3 pathway." (PMID 28046055, 2017). "Thus, in this study, we investigated the regulation of eosinophil inflammation by IL-17A and the involvement of the CCL7/CCR3 pathway in a mouse model of allergic rhinitis." (PMID 28046055, 2017). "Consequently these results suggest that IL-17A regulates eosinophil inflammation via the CCL7/CCR3 pathway in a mouse model of allergic rhinitis." (PMID 28046055, 2017). "This study was undertaken to determine whether eosinophil migration to the nasal mucosa in response to IL-17A is regulated by the CCL7/CCR3 pathway in a mouse model of allergic rhinitis." (PMID 28046055, 2017). "Further studies are warranted to evaluate AZD3778 and other CCR3-antagonists in allergic rhinitis." (PMID 20144207, 2010). "However, there are few studies on CCR3 monoclonal antibody in allergic rhinitis." (PMID 38212473, 2024). "Accordingly, CCR3-antagonists may have a potential as a treatment for allergic rhinitis." (PMID 20144207, 2010). "Our data are of interest with regard to the pharmacology of CCR3-antagonism, the relative importance of eosinophil actions to the symptomatology of allergic rhinitis, and the potential use of AZD3778 in the treatment of allergic rhinitis." (PMID 20144207, 2010).
prostate carcinoma (11 papers, 2016 to 2024). A carcinoma that arises from epithelial cells of the prostate gland. "In fact, CCL11/CCR3 have been implicated as diagnostic biomarkers in gastric cancer, prostate cancer, and ovarian cancer, and as prognostic biomarkers in renal cell carcinoma, lymphoma and ovarian cancer." (PMID 27119233, 2016). "More recently, it has been demonstrated that a prostate cancer cell line also expresses CCR3 and that the overexpression of CCR3 is significantly associated with cancer cell metastasis." (PMID 27167205, 2016). "In addition, the chemokine (C-C motif) ligand 7 (CCL7) is another factor that directs the migration of prostate cancer cells harboring its respective receptor, C-C chemokine receptor type 3 (CCR3), which is linked to poor prognosis." (PMID 39596205, 2024). "In addition, CCR3 is associated with invasion of prostate cancer cells." (PMID 34206004, 2021). "CCR3 is expressed in prostate cancer cells, and its upregulated expression has been shown to correlate significantly with cancer cell migration and invasion." (PMID 29915688, 2018). "This expression pattern favors the migration of CCR3-positive prostate cancer cells along a chemokine gradient." (PMID 29915688, 2018). "Our results highlight the clinical relevance of CCR3 expression in prostate cancer local dissemination." (PMID 26756352, 2016). "The migration of prostate cancer cells towards CM from these primary tissues also depended on the CCR3/CCL7 axis." (PMID 26756352, 2016). "These adipocytes secrete CCL7 and use of Ad-CM prepared from these cells supported prostate cancer cells migration in a CCR3-dependent manner." (PMID 26756352, 2016). "Similar results were obtained with LNCaP and C4-2B, two less aggressive prostate cancer cell lines, highlighting the role of the CCR3/CCL7 axis in the chemotaxis of prostate cancer cells in response to adipocyte secretions." (PMID 26756352, 2016). "Taken together, these results highlight that CCR3 alone is a master regulator of prostate cancer cells migration towards Ad-CM." (PMID 26756352, 2016). "Similarly, in prostate cancer mesenchymal stem cells modulate of the invasive potential of prostate cancer cells via the Eotaxin-3/CCR3 axis." (PMID 34604026, 2021). "In human prostate cancer tumours, expression of the CCR3 receptor is associated with the occurrence of aggressive disease with extended local dissemination and a higher risk of biochemical recurrence, highlighting the potential benefit of CCR3 antagonists in the treatment of prostate cancer." (PMID 26756352, 2016). "Eotaxin can increase MMP-3 expression via the CCR3-ERK pathway, thereby promoting prostate cancer cell invasion and migration." (PMID 36661524, 2023). "Although the effect of the CCR3/CCL7 axis appears predominant in the enhanced migration of prostate cancer cells, our work underlines that other chemokines and their associated receptors, might be involved in prostate cancer directed migration towards adipose tissue." (PMID 26756352, 2016). "We first verified that prostate cancer cells do not secrete this chemokine and that the inhibition of CCR3/CCL7 did not affect cell migration in response to 10% FCS." (PMID 26756352, 2016). "A CCR3 neutralizing monoclonal antibody (mAb) gave similar results (50% inhibition compared with control) and migration was unaffected by a mAb against CCR1, which is not expressed by prostate cancer cells." (PMID 26756352, 2016).
atherosclerosis (10 papers, 2012 to 2025). A disease characterized by the build-up of fatty material and calcium deposition in the arterial wall resulting in partial or complete occlusion of the arterial lumen. "Eotaxin and its receptor (CCR3) are overexpressed in human atherosclerosis and contribute to vascular inflammation." (PMID 28443978, 2017). "Of note, immunohistochemical analysis of human atherosclerosis revealed that eotaxin is predominantly located in SMCs while its receptor CCR3 in macrophage-rich regions." (PMID 27626316, 2016). "Eotaxin and its receptor, CCR3, are overexpressed in human atherosclerosis, suggesting an involvement in vascular inflammation." (PMID 26241961, 2015). "In atherosclerosis-prone mice, CCR3 deletion exacerbated vascular damage under hyperlipidemic conditions, indicating that CCR3 may play a role in maintaining the immune balance depending on the inflammatory context." (PMID 40507021, 2025). "Besides, the levels of CCL11 and its main receptor CC motif receptor 3 (CCR3) are upregulated in human atherosclerosis, suggesting that CCL11 participates in vascular inflammation." (PMID 38906863, 2024). "Few studies have analyzed the role of CCR3 in atherosclerosis." (PMID 27458015, 2016). "The protective effect of RPL13 on atherosclerosis may be related to its translational silencing activity: the deletion of RPL13 promotes the translation of mRNAs for CCL22, CXCL13, and CCR3 in macrophages, causing increased expression of inflammatory cytokines." (PMID 36617563, 2023). "In summary, RPL13 inhibits macrophage-induced inflammation and atherosclerosis by inhibiting the translation of inflammatory genes such as CCL22, CXCL13a, and CCR3." (PMID 36617563, 2023). "We found that CCR2, but not CCR3 or CCR5, participated in HDL metabolism, thus representing a potential chemokine axis of atherosclerosis." (PMID 27458015, 2016).
age-related macular degeneration (8 papers, 2010 to 2022). Age-related loss of vision in the central portion of the retina (macula), secondary to retinal degeneration. "A CCR3 inhibitor (AKST4290) combined with intravitreal anti-VEGF injections has been used to treat exudative age-related macular degeneration (AMD)." (PMID 35981418, 2022). "Interestingly, as published in Nature in 2009, CCR3 is expressed on endothelial cells in vessel overgrowth of the macula in age-related macular degeneration (AMD) and locally produced Eotaxins are thought to mediate angiogenesis in this condition [see Ref." (PMID 25759694, 2015). "Inhibition of chemokine C-C motif receptor 3 (CCR3) signaling has been considered as treatment for neovascular age-related macular degeneration (AMD)." (PMID 27309355, 2016). "Dysregulation of the CCR3/CCL11 pathway has been implicated in the pathogenesis of choroidal neovascularisation, a common feature of late age-related macular degeneration (AMD)." (PMID 24575855, 2014). "It was reported that an inhibition of CCR3 by antagonists or antibodies reduces the degree of laser-induced choroidal neovascularization in mice, a model for wet age-related macular degeneration (AMD)." (PMID 28458639, 2017).